RNU6-1315P (RNA, U6 small nuclear 1315, pseudogene)
Gene: Small nuclear RNA gene on chromosome 12 (2,954,240 to 2,954,338, reverse strand). Ensembl gene ENSG00000252996.
Homologues: Orthologues: chimpanzee U6 (96% identical), mouse Gm25039 (86% identical), macaque U6 (79% identical), guinea pig U6 (66% identical). Paralogues in human: RNU6-1309P (84% identical), RNU6-454P (84% identical), RNU6-797P (84% identical), RNU6-560P (83% identical), RNU6-1181P (82% identical), RNU6-11P (82% identical), RNU6-222P (82% identical), RNU6-238P (82% identical), RNU6-302P (82% identical), RNU6-37P (82% identical), RNU6-742P (82% identical), RNU6-879P (82% identical), and 1285 more.